HGF (hepatocyte growth factor)
Diseases named in the same sentence as HGF in open-access papers (continued):
Sharing a sentence is not in itself a finding about the gene and the disease.
cancer (continued). "HGF/c-MET signaling mobilizes neutrophils in response to cancer immunotherapies." (PMID 30400835, 2018). "In addition, HGF-MET signalling pathway is known to drive the invasive phenotype of many cancers, specifically migration and metastasis in HNSCC cells." (PMID 30001714, 2018). "In a variety of cancers however, the HGF/c-Met pathway is constitutively activated." (PMID 30134579, 2018). "Under special circumstances, such as hypoxia, cancer epithelial cells can secrete HGF." (PMID 30134579, 2018). "To verify whether the HGF-dependent pro-migratory effect of fibroblast CM was specific for A549 cells or generally applicable to other cancer cell lines, we repeated these experiments with squamous lung cancer Calu-1 cells." (PMID 29558956, 2018). "Therefore, activation of pro-HGF in the MET signaling axis is of significant importance in cancer progression, providing a rationale for targeting pro-HGF activation systems in anti-MET treatment." (PMID 30469509, 2018). "The UCB stem cells that we used secreted VEGF and HGF growth factors; therefore, we hypothesized that these cells may generate cancer cells." (PMID 30174328, 2018). "Because of the strong association between HGF/c-MET activation and human cancers, targeting HGF/c-MET by miRNAs may be a promising approach for cancer treatment." (PMID 30360560, 2018). "HGF promotes cancer cell adhesion to components of the extracellular matrix (ECM)." (PMID 30314527, 2018). "The data related to the HGF/c-Met signaling pathway and cancer suggests that the pathway inhibition may stunt the growth and progression of cancers." (PMID 30214428, 2018). "Taken together, our findings could imply the existence of a co-stimulatory loop whereby FGF-2 produced by cancer cells stimulates secretion of HGF by CAFs which in turn promotes migration and aggressiveness of cancer cells." (PMID 29558956, 2018). "A549 cells stimulated with CM containing high levels of HGF migrated significantly more rapidly compared to those stimulated with low-HGF CM, and the HGF-neutralizing antibody partially abrogated this effect, thus confirming the role of fibroblast-derived HGF in promoting motility of cancer cells." (PMID 29558956, 2018). "TME represents a significant source of HGF, which may trigger signaling cascades in cancer cells, thus fostering their survival and dissemination." (PMID 30544501, 2018). "HGF is an important mediator of interactions between cancer cells and stroma cells." (PMID 30513872, 2018). "The generation of a MET/HGF autocrine loop by anomalous co-expression of ligand and receptor in the same cell is another way by which cancer cells may achieve continuous MET activation." (PMID 30544501, 2018). "Therefore, HGF-regulated actin rearrangement is mainly through the regulation of small GTPase activity, but different types of cancer cells utilize distinct combinations of the signaling pathway in response to HGF to activate small GTPases." (PMID 28475121, 2017). "Thus, agents blocking the biological activity of HGF, such as inhibitors of pro-HGF activation, should be incorporated into therapeutic regimens for a selected population of cancer patients." (PMID 28420162, 2017). "HGF regulation of cancer cell metastasis may, through modulate cell-cell junctions’ stability and the expression of the component proteins." (PMID 28475121, 2017). "Exosome-mediated EGFR activates liver HGF, thus preparing ‘soil' for future cancer cell metastasis." (PMID 28393839, 2017). "Since several substrates of matriptase, such as urokinase (uPA), stromelysin (MMP3), pro-HGF (hepatocyte growth factor), and PAR2 (protease-activated receptor 2), were implicated in cancer progression, the role of matriptase in cancers has been intensely addressed recently." (PMID 29118397, 2017).
cancer (continued). "We observed that the supernatants from both HGF- or CsA-treated cancer cells increased the number of endothelial tubes formed compared with control; whereas the supernatants from cells grown in the presence of HNK significantly inhibited the tube formation ability of HUVEC cells." (PMID 28724911, 2017). "In addition, fibroblasts (or recombinant HGF) promote survival of cancer cells and represent an important source of primary and acquired resistance to targeted therapy, including inhibitors of EGFR." (PMID 28420162, 2017). "In general, autocrine production of HGF by cancer cells occurs infrequently." (PMID 28420162, 2017). "Aberrant activation of the HGF/c-Met signaling pathway has been reported in numerous human cancers." (PMID 28902178, 2017). "Hence, exosomes secreted from primary gastric tumour regulate liver micro-environment to promote liver metastasis and the upregulated liver paracrine HGF provides fertile ‘soil' for the metastatic cancer cells." (PMID 28393839, 2017). "Cancer cells may secrete molecules to trigger HGF expression in stromal fibroblasts, which in turn stimulate the progression of cancer cells." (PMID 28587113, 2017). "Finally, myofibroblasts have been shown to promote Wnt signalling and foster cancer stem cell phenotype by promoting Wnt signaling through production of hepatocyte growth factor (HGF)." (PMID 28420162, 2017). "c-MET and its ligand hepatocyte growth factor are often dysregulated in human cancers." (PMID 28315949, 2017). "Moreover, we and others have demonstrated that inhibition of both MET and HGF is required to overcome therapeutic resistance in MET-amplified cancer cells." (PMID 28420162, 2017). "C-MET is the receptor of HGF and is widely expressed in various types of cancer." (PMID 28393839, 2017). "These clinical studies give rise to an idea that the effect of pazopanib on cancers with active HGF/c-MET signalling might be limited." (PMID 28511645, 2017). "This review will focus on recent progress on the role of c-Met/HGF signaling in cytoskeleton protein dynamics and spacious rearrangements, and the related signaling molecules that are aberrantly activated, which lead to cancer migration and metastasis." (PMID 28475121, 2017). "MET, the receptor tyrosine kinase (RTK) for scatter factor/hepatocyte growth factor, is involved in acquisition and maintenance of critical oncogenic and invasive features in several types of human cancer and represents a promising molecular therapeutic target." (PMID 28532501, 2017). "Altogether, our results indicate that BsAb inhibits HGF-mediated proliferation, migration, and antiapoptosis effects in cancer cells, and could serve as an inhibitory c-MET antibody." (PMID 28404966, 2017). "Indeed, cancer-associated fibroblasts have been shown to promote growth, survival and migration of cancer cells in an HGF-dependent manner." (PMID 28420162, 2017). "In addition, binding of HGF to c-MET increases production of uPA in cancer cells, which further activates precursor HGF to active HGF, thus forming a feed forward loop." (PMID 29100344, 2017). "Our data on HGF secretion from pancreatic stellate cells suggest that the complexity of signal communication between stromal cells and cancer cells is further complicated by the existence of differentially expressed signaling pathways among stellate cells isolated from different patients." (PMID 29069737, 2017). "We put emphasis on novel aspects of cancer-associated c-Met expression regulation on both, HGF-dependent and HGF-independent non-canonical mechanisms." (PMID 28212658, 2017). "Furthermore, the inhibitory effect of HGF-induced cancer cell growth of IRCR201 was superior to that of huOA5D5.v2." (PMID 28902178, 2017). "The role of MT in HGF-induced cancer cell migration and invasion may achieve, through its role as a mediator of signaling molecules, transportation from the cytosol to the cell membrane." (PMID 28475121, 2017).
cancer (continued). "EMT can be induced by growth factors such as transforming growth factor beta (TGF-β), epidermal growth factor (EGF), hepatocyte growth factor (HGF), insulin-like growth factors 1 and 2, activating RAS, Notch, and Wnt signalings which have been associated with poor prognosis and cancer progression." (PMID 29189742, 2017). "Albeit the battery of experimental results that investigate the biological functions of miR-7 and HGF in cancer cells, there are presently no reported association between them." (PMID 29133945, 2017). "Collectively, previous studies have found a critical role for the c-Met/HGF pathway in cancer proliferation and metastasis, indicating that the c-Met/HGF may be a viable target for future therapy development." (PMID 28315228, 2017). "Furthermore, in a study utilizing immortalized fibroblasts, it has been suggested that TGFβ negatively regulates HGF expression and HGF-induced cancer cell invasion." (PMID 29069737, 2017). "Some cancer cells produce HGF which stimulates MET in an autocrine manner." (PMID 28420162, 2017). "Importantly, understanding the mechanisms that mediate HGF-induced cancer cell cytoskeleton dynamic reorganization has implications for the development of effective anti-metastasis cancer drugs." (PMID 28475121, 2017). "The hepatocyte growth factor (HGF)/c‐Met signaling axis is a potential target for cancer therapy." (PMID 28164434, 2017). "Taken together, regulation of microfilaments by HGF in cancer cells relies on various mechanisms." (PMID 28475121, 2017). "Thus, molecular markers of CAFs, such as fibroblast activation protein (FAP), C-X-C motif chemokine ligand 12 (CXCL12), and hepatocyte growth factor (HGF) are emerging as selective therapeutic targets in the cancer stroma." (PMID 28346486, 2017). "In a significant number of human cancers, HGF/SF and MET are overexpressed." (PMID 28061464, 2017). "The HGF–cMET pathway is a promising target for cancer therapy." (PMID 28336955, 2017). "Importantly we also found that reduced PAK4 expression significantly reduced the level of cancer cell invasion in the HGF-mediated organotypic invasion assay." (PMID 28205613, 2017). "Cancer cells stimulate stromal fibroblasts to secrete inactive HGF proform (proHGF)." (PMID 29202869, 2017). "HGF-producing cancer cells display autocrine activation of MET signaling." (PMID 27121052, 2016). "The findings reported here also indicate that inhibitors of HGF activation overcome primary and acquired resistance to anti-EGFR therapy, providing a rationale for concurrent inhibition of EGFR and HGF to prevent therapeutic resistance and to improve the outcome of cancer patients." (PMID 27121052, 2016). "Indeed, we show here using cell scattering and scratch wound healing assays that cloudberry extract strongly inhibits HGF-induced and Met receptor-mediated cancer cell migration, a prerequisite for cancer cells to metastasize." (PMID 27270323, 2016). "Therefore, inhibition of the HGF/c-Met signaling axis has a great potential for therapeutic intervention in cancer." (PMID 27086914, 2016). "MET/HGF has been regarded as a promising therapeutic target in cancer treatment, whose gene or protein status may be indicative of patient response to MET-targeted drugs." (PMID 27013592, 2016). "Thus, triplex inhibitors, such as SRI 31215, will efficiently interfere with activation of pro-HGF in cancer cells that display expression/activation of multiple proteases." (PMID 27121052, 2016). "Similarly, although MET kinase inhibitors curb the growth of leukemic cells that are addicted to HGF/MET signaling, cancer cells rapidly develop resistance to MET kinase inhibitors due to compensatory upregulation of HGF." (PMID 27121052, 2016).
cancer (continued). "Our previous research found that maoto, an Ephedra Herb-containing formulation, suppressed cancer metastasis by inhibiting cancer cell motility and prevented hepatocyte growth factor (HGF)-induced cancer cell motility by inhibiting phosphorylation of the c-Met receptor." (PMID 26943796, 2016). "However, the HGF/c-Met axis is frequently reactivated by cancer cells for tumorigenesis, invasive growth, and metastatic progression." (PMID 27086914, 2016). "In addition, HGF is well known as a potent angiogenic cytokine, and c-Met signal activation can modify the microenvironment to facilitate cancer progression." (PMID 26919096, 2016). "HGF is known to have important roles in cancer progression through its specific receptor, MET." (PMID 27612426, 2016). "Furthermore, elevated HGF, a ligand for c-met and NRP-1 that is involved in epithelial-mesenchymal transition and metastatic behavior of cancer cells was significantly associated with NRP-1 expression." (PMID 26701889, 2016). "Meanwhile, MACC1 could be bound to the promoter of the MET gene and activate the HGF/MET signaling pathway to promote cancer cell proliferation, invasion, and metastasis." (PMID 27793161, 2016). "Together with MACC1-regulating cancer growth via the activation of the HGF/c-MET/PI3K/AKT signaling pathway, we purposed that MACC1 might induce trastuzumab resistance by regulating the Warburg effect via the PI3K/AKT signaling pathway." (PMID 27581375, 2016). "The hepatocyte growth factor (HGF)/mesenchymal-epithelial transition factor (c-Met) signaling axis has gained considerable attention as an attractive molecular target for therapeutic blockade of cancer." (PMID 27086914, 2016). "Our results showed that the percentage of high HGF expression in cancer cells was 82.1%." (PMID 27374174, 2016). "HGF was identified as a scatter factor for its ability to induce scattering of cancer cells." (PMID 27121052, 2016). "As expected, HGF increased the speed of migration of both cancer cells." (PMID 26310485, 2015). "Indeed, higher expression of the c-MET receptor in different cancer cell lines correlated with their resistance to targeted therapy stimulated by HGF." (PMID 26090722, 2015). "In particular, the role of HGF as mediator of the interactions between cancerous cells and adjacent stroma seems to be fundamental to create a microenvironment that promotes the further development and invasiveness of cancer." (PMID 28536400, 2015). "For all above reasons MET could become a valuable target for cancer therapy and several drugs targeting MET or its ligand HGF are currently undergoing early phase clinical trials in various cancers." (PMID 26580964, 2015). "Therefore, activation of the HGF/c-Met pathway results in the simultaneous activation of multiple signal transduction pathways that promote cancer cell infiltration." (PMID 25592281, 2015). "Given that the pro-survival role of the PI3K/AKT activation is associated with chemoresistance of cancers, we examined whether the blockade of PI3K/AKT could reverse the HGF-induced resistance to paclitaxel." (PMID 26115510, 2015). "Therefore, if the c-Met receptor is present in cancer cells, HGF antagonists should be able to inhibit multiple signal transduction pathways that lead to cancer cell infiltration, thereby exerting potential anti-cancer effects." (PMID 25592281, 2015). "In addition to this, we investigated the effects of anti-HGF monoclonal antibody on cancer chemoresistance." (PMID 26090722, 2015). "Following Cox-2 inhibition, we observed reduced infiltration of tumors with cancer-associated fibroblasts (CAFs) and lower levels of pro-angiogenic factors active besides the VEGF axis including hepatocyte growth factor (HGF) and basic fibroblast growth factor (FGF2)." (PMID 25849942, 2015). "Potentially, pharmacological agents that disrupt the HUWE1-TIAM1 interaction could be beneficial in decreasing the HGF/MET-driven metastatic dissemination of cancer cells." (PMID 25543140, 2015).
cancer (continued). "HGF and its receptor c-Met play an important role in the development of various cancer types." (PMID 25885021, 2015). "Most cancers express both HGF and c-Met, leading to autocrine activation of c-Met." (PMID 25971889, 2015). "The HGF level is frequently increased in advanced cancer patients." (PMID 25436000, 2015). "Regarding intracellular signaling, LZ8 may suppress the protein kinase C-dependent pathway involved in cancer progression triggered by HGF-c-Met." (PMID 25607934, 2015). "Therefore, development of agents targeting to components in HGF/MET pathway is a potential therapeutic strategy for many cancers." (PMID 26254225, 2015). "Because cancer associated stroma are implicated in supporting angiogenesis, we examined the possible effects of exosome-driven differentiation on angiogenic factors VEGF-A and HGF." (PMID 25596732, 2015). "Moreover, motility of cancer cells and ECs in response to HGF was reduced upon treatment with INC280." (PMID 25884642, 2015). "c-Met, a receptor for hepatocyte growth factor (HGF), which is a promoter of cancer progression, has several major alternative downstream pathways in its signaling cascade: Akt 1, 2 and 3 (protein kinase B), signal transducer and activator of transcription 3 (STAT3), and MAPK." (PMID 25633810, 2015). "Our current data implies that PLCγ may act in a similar fashion as that seen in cancer cells’ responses to HGF, acting to facilitate HGFl pro-migratory effects in keratinocytes." (PMID 28536402, 2015). "Additionally, HGF-induced adhesion of cancer cells to peritoneal tissue is significantly decreased by INC280 treatment." (PMID 26138303, 2015). "Therefore, little is known about the effects of HGF-induced metabolic reprogramming on cancer development and recurrence." (PMID 26099202, 2015). "Thus, inhibition on HGF-initiated MET signaling pathway would provide a new approach to cancer targeted therapeutics." (PMID 26254225, 2015). "In addition, many other known flavonoids, such as EGCC, luteolin, kaempferol and myricetin also showed inhibitory effects on HGF-stimulated cancer cells migration." (PMID 25971889, 2015). "Thus, silencing of two major functional domains that regulate HGF/c-MET signaling represents a promising therapeutic strategy in targeting this driver of cancer." (PMID 25726528, 2015). "HGF is the only known ligand for c-MET and c-MET has clearly been associated with aggressive disease, poor prognosis, worse clinical outcomes, and chemoresistance in many cancers." (PMID 26404380, 2015). "Since tumorigenesis may involve the dysregulation of the MET signaling pathway, changes in HGF or MET signaling are expected to be potential biomarkers for understanding cancer development and the effect of drugs." (PMID 28536405, 2015). "Thus, we have focused on evaluating the clinical significance of HGF/c-Met axis in cancer chemotherapy." (PMID 26090722, 2015). "Hepatocyte growth factor (HGF) expression is a poor prognostic factor in various types of cancer." (PMID 25436000, 2015). "Taken together, although high HGF levels might indicate enhanced activation of the MET signaling pathway in cancer development, these data should be cautiously interpreted due to their limited predictive value for clinical response." (PMID 28536405, 2015). "In addition, the antiproliferative activity of (-)-oleocanthal was accomplished in cancer cells maintained in the presence of HGF as well as in HGF-free treatment media." (PMID 24849787, 2014). "A recent review indicated that enhanced HGF/Met signaling is found in various types of cancers." (PMID 25521854, 2014). "In addition, aberrant activation of the HGF/c-Met axis is known to promote cytoskeletal changes of many cancer cells in favor for migration, invasion, and eventual metastasis." (PMID 24849787, 2014). "The HGF/c-Met signature is highly expressed in almost 90% of basal-like cancers from patients." (PMID 25072025, 2014).